BARD1 (BRCA1 associated RING domain 1)
Diseases named in the same sentence as BARD1 in open-access papers (continued):
Sharing a sentence is not in itself a finding about the gene and the disease.
neuroblastoma (continued). "In addition of the female specific cancers, BARD1 SNPs have been found to be associated with neuroblastoma." (PMID 23056176, 2012). "Additionally, clinically relevant germline variants were detected in four cancer-associated genes, including an SBDS splice-site mutation (c.258 + 2T > C) in a rhabdomyosarcoma, BARD1 p.E652fs*69 in a neuroblastoma, EP300 p.A2259fs*20, and EXT2 p.W414* in two osteosarcoma patients." (PMID 35585047, 2022). "However, there are abundant BARD1 isoforms exist that are different from the full-length BARD1 due to nonsense and frameshift mutations, or deletions were found to be associated with susceptibility to various cancers including neuroblastoma, lung, breast, and cervical cancers." (PMID 35650591, 2022). "Four pathogenic or likely pathogenic germline BARD1 variants (those which are capable or likely capable of disrupting function/causing disease, denoted in red) were found in patients diagnosed with pediatric cancers including neuroblastoma, glioma, and B-cell acute lymphoblastic leukemia." (PMID 36187937, 2022). "The BARD1 rs17489363 and rs1048108 polymorphisms could influence neuroblastoma susceptibility." (PMID 31123171, 2019). "The expression of certain BARD1 isoforms is upregulated in a wide range of malignancies, including breast, ovarian, uterine, lung, neuroblastoma, melanoma, leukemia, and colon cancers." (PMID 41009605, 2025). "Three BARD1 gene polymorphisms (rs7585356 GNA, rs6435862 TNG, and rs3768716 ANG) were highly associated with neuroblastoma risk." (PMID 35650591, 2022). "The best-analyzed is neuroblastoma, but only limited data on BARD1 is available for Wilms’ tumour, case studies in Ewing sarcoma, and osteosarcoma or does not exist as in case of GCT or RMS." (PMID 33530592, 2021). "Comparing the expression in groups of different types of childhood tumours, a higher level of BARD1 FL in neuroblastoma (FL: 0.0128 ± 0.0135; β: 0.0045 ± 0.0054) series is noticeable." (PMID 33530592, 2021). "BARD1 alternative isoforms have been described, among others, in the colorectal, lung, gynaecological cancers, and neuroblastoma." (PMID 33530592, 2021). "When compared neuroblastoma group to GCTs (FL: 0.057 ± 0.0055; β: 0.0029 ± 0.0022), in which case expression of BARD1 FL is on the lowest level, difference reaches statistical significance (Z = 2.53; p = 0.039)." (PMID 33530592, 2021). "We previously reported that the repression of FL BARD1 is crucial for neuroblastoma cells proliferation and invasion." (PMID 32047556, 2020). "Firstly, we carried out a correlation analysis between FL BARD1 expression versus all genes in 161 neuroblastomas profiled by RNAseq that allows distinguishing among alternative spliced transcripts." (PMID 32047556, 2020). "In the present study, we show that FL BARD1 expression correlates with the expression of genes involved in DNA repair and cell cycle in neuroblastoma samples, probably due to BARD1/BRCA1 heterodimer function." (PMID 32047556, 2020). "We found high-risk variants that fall into promoter correlate with low expression of FL BARD1 and with neuroblastoma development." (PMID 32047556, 2020). "Here we show that FL BARD1, as part of the heterodimer BRCA1/BARD1, prevent unscheduled mitotic entry of DNA damaged neuroblastoma cells via a mechanism requiring downregulation of cyclin B/Cdk1 and cell cycle arrest at the G2-M boundary." (PMID 32047556, 2020). "We demonstrated that FL BARD1 depletion influences clonogenic activity in post-DNA damaged neuroblastoma cells." (PMID 32047556, 2020). "We show that FL BARD1 is involved in DNA damage response and FL BARD1 depletion allows neuroblastoma cells to proceed in mitosis by avoiding cell cycle checkpoints." (PMID 32047556, 2020). "Subsequently, we obtained 25 verified neuroblastoma specimens from the University of Chicago pathology archive and examined nuclear BARD1 and p50 in contiguous sections." (PMID 33024116, 2020).
neuroblastoma (continued). "Here we have investigated the mechanisms of FL BARD1 in neuroblastoma cell lines depleted for FL BARD1 expression." (PMID 32047556, 2020). "Later on, the same group reported that common variants in BARD1 gene were associated with high-risk neuroblastoma, and polymorphisms within DUSP12, DDX4, IL31RA, and HSD17B12 were associated with low-risk neuroblastoma." (PMID 31341530, 2019). "Low expression of Bard1 induces proliferation and invasion of neuroblastoma cells indicating that Bard1 has a tumor suppressor function in neuroblastoma." (PMID 30760980, 2019). "GNB1 is also affected by APA in a PCF11-like manner upon depletion of BARD1 (see TREND-DB), one of the few factors in which germline mutations have been linked to neuroblastoma formation." (PMID 30552333, 2018). "Oncogenic action of BARD1 in neuroblastoma has been demonstrated to be exerted by stabilizing AURKA involved in aggressive neuroblastomas." (PMID 28467792, 2017). "Citalopram drastically decreased the expression of MYBL2, BIRC5 and BARD1 poor prognosis factors of neuroblastoma with fold-changes of -107 (p<2.26 10−7), -24.1 (p<5.6 10−9) and -17.7 (p<1.2 10−7)." (PMID 28467792, 2017). "Here, we show that there may be a specific BARD1 isoforms pattern in germ cell tumors, rhabdomyosarcoma, and neuroblastoma subtypes." (PMID 33530592, 2021). "The majority (n = 84/89; 94.4%) of neuroblastoma samples expressed BARD1 FL." (PMID 33530592, 2021). "We obtained a series of neuroblastoma cell lines and examined BARD1 and p50 protein in these cells." (PMID 33024116, 2020). "In this study, we further investigated FL BARD1 in neuroblastoma cells to support the hypothesis of its role as tumor suppressor gene." (PMID 32047556, 2020). "We also detected rare genetic germline variants in DNA repair genes (e.g., BARD1, BRCA2, CHEK2, and WRN) that might cooperate with somatically acquired variants in these patients with highly aggressive recurrent neuroblastoma." (PMID 33384420, 2020). "Moreover, several genome-wide association studies (GWASs) have identified extra neuroblastoma susceptibility genes, including CASC15, BARD1, LMO1, DUSP12, HACE1, LIN28B, CPZ and RSRC1." (PMID 31123171, 2019). "Other genetic mutations, such as SNPs in the ALK and BARD1 genes and copy number polymorphism of NBPF23, may also have a role in neuroblastoma development." (PMID 30285664, 2018). "By studying the association of mutational variants of candidate neuroblastoma genes with clinical, cytogenetic and pathological characteristics, and survival outcomes, we found 1p candidate genes CHD5 and KIF1Bβ to be most frequently mutated after ALK, ATRX, and BARD1." (PMID 35768791, 2022). "However whilst both BARD1 SNPs (rs2070096, rs2229571) in this study have been associated with nephroblastoma and neuroblastoma, no studies have associated them with response to platinum based drugs as part of a therapeutic regimen." (PMID 30071039, 2018). "In vitro repression of BARD1β caused SNP genotype-specific inhibition of cell proliferation in neuroblastoma cells, and overexpression of BARD1β, but not FL BARD1, led to the transformation of non-malignant fibroblasts, suggesting that BARD1β is an oncogenic driver of high-risk neuroblastoma." (PMID 28030839, 2017). "Among all the factors taking part in NB tumorigenesis, recent genomic and functional investigations highlighted BARD1, LMO1, and ASCL1 as important actors in neuroblastoma tumorigenesis as well." (PMID 34884690, 2021). "Additionally, it was shown that common variants in BARD1 that are not the subject of this study may also modify cancer risk, including lung cancer and neuroblastoma." (PMID 32679805, 2020).
neuroblastoma (continued). "We will then focus on evaluating the common BARD1 related SNPs as well as genetic and epigenetic changes that occur in the non-BRCA1-dominant cancers, including neuroblastoma, lung, and gastrointestinal cancers." (PMID 32708251, 2020). "We specifically studied MYCN, MYBL2, BIRC5, BARD1 and AURKA, poor prognosis markers of neuroblastoma, and CCNA2 and CCNE1 genes, involved in general carcinogenesis." (PMID 28467792, 2017). "We verified that this antibody only recognized FL BARD1 and not other isoforms by immunoblot in neuroblastoma cell lines." (PMID 33024116, 2020). "Although we have previously shown that down-regulation of FL BARD1 has oncogenic effects 13, a role for FL BARD1 as tumor suppressor gene has not been examined in neuroblastoma cells." (PMID 32047556, 2020). "However, our results do not demonstrate a correlation between expression of BARD1 β and patho-clinical features in neuroblastoma and lack of BARD1 β (but not BARD1 FL) did not correlate with more favourable phenotype." (PMID 33530592, 2021).
triple-negative breast carcinoma (17 papers, 2015 to 2025). An invasive breast carcinoma which is negative for expression of estrogen receptor (ER), progesterone receptor (PR), and human epidermal growth factor receptor 2 (HER2). "Pathogenic BARD1 variants have been shown to moderately increase the risk of developing triple-negative breast cancer." (PMID 40869938, 2025). "Analysis of the whole-genome sequencing data from a triple-negative breast cancer (TNBC) patient’s germline DNA uncovered a c.403G>A (p.Asp135Asn) mutation in BARD1." (PMID 33933153, 2021). "Our results added evidence that the inherited c.403G>A mutation in the highly conserved functional domain of BARD1 appears to suggest a favorable response of a triple-negative breast cancer patient to a PARP inhibitor, thus benefiting patients beyond carriers of BRCA1 or BRCA2 germline mutations." (PMID 33933153, 2021). "An enrichment of BARD1 PVs among triple-negative breast cancer (TNBC) cases has also been evidenced." (PMID 33498765, 2021). "NUSAP1 expression was correlated with BRCA1, BRCA2, and BARD1 expression, and upregulation of NUSAP1 predicted poor prognosis in triple-negative breast cancer." (PMID 30678687, 2019). "Among the BARD1 mutants, the majority of the breast tumors were invasive ductal carcinoma (NOS type) (10/11, 90.9%) of high-grade disease (9/9, 100%) and half of them were triple-negative breast cancer (5/10, 50%)." (PMID 40805222, 2025). "Additionally, a germline deletion of the entire BARD1 gene was detected in a non-BRCA patient with triple-negative breast cancer." (PMID 25994375, 2015).
pancreatic cancer (14 papers, 2017 to 2025). "In pancreatic cancer specifically, several rare BARD1 variants have been identified in both familial and sporadic cases." (PMID 41009605, 2025). "Both germline and somatic BARD1 mutations have been described in pancreatic cancer, supporting BARD1’s role in tumor suppression; as such, BARD1 is currently included in germline mutation testing panels, along with other DNA repair genes." (PMID 41009605, 2025). "The BARD1 c.1333G>T variant occurred with BRCA2 c.1658T>G (p.Leu553Ter) in early onset TNBC women diagnosed with pancreatic cancer at the age of 32." (PMID 34646395, 2021). "They identified a mutation in BARD1 c.1921C > T p.Arg641X in a PDAC patient who had one relative with pancreatic cancer that resulted in a premature stop." (PMID 32708251, 2020). "Novel germline mutations in the BARD1 gene have been identified in pancreatic cancers, arising from either neuroendocrine or exocrine ductal cells, however, their function and role in susceptibility have yet to be validated." (PMID 32708251, 2020). "Thus, mutations in BARD1 can lead to the development of pancreatic cancers originating from neuroendocrine cells." (PMID 32708251, 2020). "The role of DCAFs in mediating BARD1 degradation in pancreatic cancer remains to be explored." (PMID 41009605, 2025). "Likewise, pancreatic cancer stem cells isolated from human tumors also display increased expression of the binding partner of BARD1, BRCA1, enhancing their capacity to survive Gemcitabine treatment." (PMID 41009605, 2025). "Reduced expression of such miRNAs, coupled with overexpression of BARD1 isoforms, may contribute to tumor progression, an area that remains largely unexplored in pancreatic cancer." (PMID 41009605, 2025). "Interestingly, we observed that there are reports of mutations and copy number variation in PAIP2B, PRDX1, RNASE1, BARD1, UHMK1, and RPL3L genes associated with pancreatic cancer." (PMID 34912796, 2021). "Additionally, analysis of lymphoblasts from 100 familial pancreatic cancer patients detected two SNPs in BARD1, rs2229571 and rs1129804, which had profound effects on its gene expression (greater than 4-fold change)." (PMID 32708251, 2020). "MGPTs generally cover at least 10 common HR-related genes such as ATM, BARD1, BRCA1, BRCA2, BRIP1, CHEK2, NBS1 (NBN), PALB2, RAD51C, and RAD51D, all of whose germline alterations are associated with BRCAness phenotypes for predisposition to breast, ovarian, prostate, or pancreatic cancer." (PMID 35008774, 2021). "Mutations in the BARD1 gene were appreciated in 20–25% of tumor samples taken from the pancreas and the adrenal gland; however, the cohorts were very small and may not reflect the true prevalence of BARD1 mutations in pancreatic cancer and NB." (PMID 32708251, 2020). "Our group previously published that HuR regulates BARD1 expression in pancreatic cancer cells through a non-canonical mechanism involving both pre-mRNA and mature mRNA transcript levels." (PMID 41009605, 2025).
lung carcinoma (13 papers, 2013 to 2025). "Antibodies against cancer-associated isoforms of BARD1 can be detected in the serum of lung cancer patients." (PMID 28786985, 2017). "BARD1 isoforms have been associated with lung cancer progression." (PMID 28786985, 2017). "We hypothesized that BARD1 (BRCA1-associated RING domain 1), which is aberrantly expressed and correlated with poor prognosis in lung cancer, might be involved in lung fibrosis." (PMID 26415510, 2015). "In lung cancer, lncRNA BARD1 9'L, transcribed from an alternative promoter in intron 9 of the BARD1 gene and shared part of the 3'UTR with the protein coding BARD1 mRNAs, counteracted the effect of miR-203 and miR-101, to promote tumor development." (PMID 31164492, 2019). "Using fitted Lasso logistic regression we determined the optimal combination of BARD1 antigens to be used in ELISA for discriminating lung cancer from healthy controls." (PMID 28786985, 2017). "Here, we show that a panel of BARD1 peptides for the creation of complex autoantibody profiles allows the differentiation of lung cancer patients from healthy blood donors with high accuracy." (PMID 28786985, 2017). "The BRCA1 and BARD1 genes and proteins play crucial role in the development of various cancers other than lung cancer." (PMID 28786985, 2017). "We tested 194 blood samples from healthy donors and lung cancer patients with a panel of 40 BARD1 antigens." (PMID 28786985, 2017). "As BARD1 isoforms are tell tales of tumor progression and TAAs, we thought to develop a blood test for the early detection and diagnosis of lung cancer based on capturing autoimmune antibodies against BARD1 antigens." (PMID 28786985, 2017). "To determine the presence of anti-BARD1 antibodies in cancer patients, we tested sera from patients with lung cancers and controls with 33 peptides and seven BARD1 fragments in ELISA assays." (PMID 28786985, 2017). "We aimed to develop a simple reliable blood test for early detection of all types of lung cancer based on the immunogenicity of aberrant forms of BARD1 that are specifically upregulated in lung cancer." (PMID 28786985, 2017). "There appears to be no established association between BARD1 and ovarian, pancreatic, or lung cancer; however, larger studies are needed to confirm these findings." (PMID 40649708, 2025). "Therefore autoimmune antibodies against BARD1 in lung cancer patients are reflect the existence of tumorigenic BARd1 isoforms and are tell tales of cancer." (PMID 28786985, 2017). "Moreover, expression of truncated BARD1 isoforms has been correlated with poor prognostic factors in breast, ovarian and lung cancer, suggesting a pro-tumorigenic function of the isoforms." (PMID 24349422, 2013). "Interestingly, we also identified pancreatic and lung cancer in two patients carrying PVs in BARD1." (PMID 40649708, 2025). "The expression level of BARD1 isoforms correlated with decreased disease free survival and overall survival of NSCLC patients and with tumor progression in an animal model of lung cancer." (PMID 28786985, 2017). "Multiple BARD1 isoforms are overexpressed in various cancer, with a particular combination of isoforms in lung cancer, while the expression of full length (FL) BARD1 is absent or reduced." (PMID 28786985, 2017). "Moreover, no studies have investigated circulating levels of BARD1, including in serum and urine, although one study analysed serum autoantibody against BARD1 as a biomarker of lung cancer, not BARD1 itself." (PMID 32934343, 2020). "Therefore, the simple detection of antibodies against BARD1 isoforms in blood sera can accurately predict the presence of lung cancer, regardless of stage." (PMID 32708251, 2020).
Fanconi anemia (12 papers, 2017 to 2025). Fanconi anemia (FA) is a hereditary DNA repair disorder characterized by progressive pancytopenia with bone marrow failure, variable congenital malformations and predisposition to develop hematological or solid tumors. "In CRC, significant associations of HR (BRCA1, BRCA2, BARD1, PALB2 and BRIP1) and Fanconi anaemia (FANCA, FANCC and FANCG) genes with TMB were identified." (PMID 37821580, 2023). "In our experiments, the most significant upregulated genes included FANCD2, a player in Fanconi anemia (FA), and several genes playing a role in the HR-mediated repair of double-strand breaks (DSBs) such as BARD1, BRCA2, RAD51 and DNA2." (PMID 36672885, 2023). "In our work, transcriptomic studies revealed that functions involved in DNA damage such as those classified as ATM, ATR, Fanconi Anemia, and BARD1 pathways are clearly dysregulated in breast tumors, particularly in the basal-like and HER2 subtype." (PMID 33925616, 2021). "Genes included in different pathways, such as ATM/ATR, BARD1, and Fanconi Anemia, which are involved in the DNA damage response, were selected and confirmed using molecular alterations data contained at cBioportal." (PMID 33925616, 2021). "Overall, 14.6% had mutations in BRCA1 or BRCA2, 3.3% had mutations in other BRCA–Fanconi anemia genes (BRIP1, PALB2, RAD51C, RAD51D, BARD1), and 0.4% had mutations in mismatch repair genes linked to Lynch syndrome." (PMID 32679669, 2020). "Other defects in homologous recombination repair genes, such as EMSY, RAD51, ATM, ATR, Fanconi anemia, BARD1, BRIP1, PALB2, RB1, NF1, CDKN2A, and the suppression of BRCA1 transcriptional activation through gene methylation, are associated with homologous recombination deficiency (HRD)." (PMID 32679669, 2020).